LGALS3 (galectin 3)
Diseases named in the same sentence as LGALS3 in open-access papers (continued):
Sharing a sentence is not in itself a finding about the gene and the disease.
myocardial infarction (95 papers, 2014 to 2026). Gross necrosis of the myocardium, as a result of interruption of the blood supply to the area, as in coronary thrombosis. "Another study analyzed the utility of galectin-3 in patients with acute myocardial infarction and reported that elevated galectin-3 is significantly associated with remodeling, cardiac function, and clinical outcomes." (PMID 40747494, 2025). "A similar meta-analysis from 2020 suggested a positive association between elevated galectin 3 levels and all-cause mortality among people who had suffered an acute myocardial infarction." (PMID 38541144, 2024). "Elevated levels of galectin-3 in patients with acute myocardial infarction were associated with the development of major adverse cardiovascular outcome." (PMID 36362577, 2022). "A recent analysis of patients with AMI revealed that elevated levels of galectin-3 were associated with a 4.4 times higher risk of developing atrial fibrillation, suggesting that Gal-3 could be a prognostic biomarker in acute myocardial infarction." (PMID 39274304, 2024). "Our aims were to examine the association of their haplotypes with first myocardial infarction (MI), changes in left ventricular echocardiographic parameters over time, and impact on plasma galectin-3 and LGALS-3 mRNA in peripheral blood mononuclear cells, both 6 months post-MI." (PMID 36672849, 2022). "Furthermore, in post-myocardial infarction patients, it was shown that plasma Galectin-3 levels predict a high risk of deleterious vascular dysfunctions at 6 months." (PMID 33287402, 2020). "Galectin 3 turned out to provide information about all-cause mortality, while Galectin 3 binding protein proved to be of better utility in predicting the risk or recurrent angina with the need of revascularization/hospitalization or myocardial infarction." (PMID 31035456, 2019). "A randomized controlled trial compared the effects of high-dose atorvastatin (80 mg/d) and rosuvastatin (40 mg/d) on serum galectin-3 levels in patients with acute myocardial infarction." (PMID 40918185, 2025). "Previous studies on myocardial infarction have demonstrated that Lgals3 can promote the recruitment of macrophages to the infarcted myocardium and exerts a vital role in the repair phase." (PMID 40458459, 2025). "In our study, blood samples were collected only once, six months after the first myocardial infarction, and LGALS-3 mRNA expression and gal-3 levels in plasma were determined from those samples." (PMID 39767568, 2024). "Nevertheless, it has been established that galectin-3 has a predictive significance on the development of myocardial dysfunction after acute myocardial infarction (AMI) and that the use of mineralocorticoid receptor antagonists reduces its level." (PMID 35208606, 2022). "A high concentration of galectin-3 and MR-proANP observed on admission inpatients with acute myocardial infarction has significant prognostic value: itmay identify patients at high risk of early adverse cardiac events after AMI." (PMID 39077714, 2022). "In experimental models, an increased level of galectin-3 was associated with acute respiratory distress syndrome (ARDS)-induced cardiac damage, as well as acute myocardial infarction-induced cardiac remodeling." (PMID 36362577, 2022). "In the mice myocardial infarction model, genetic deletion of galectin-3 altered the temporal evolution of macrophage infiltration and wound healing, which affected cardiac remodeling and function." (PMID 35479285, 2022). "In the present study, we analyzed tag variants covering more than 80% of the variability of the haplotype block containing LGALS-3, in association with the first acute myocardial infarction, LGALS-3 expression, and plasma Gal-3 concentrations 6 months post-MI." (PMID 36672849, 2022). "Galectin-3 is released in acute coronary syndrome during the acute phase of acute myocardial infarction." (PMID 35683362, 2022).
myocardial infarction (continued). "The IL-10–STAT3–galectin-3 axis was essential to generate SPP1 for reparative macrophage polarization after myocardial infarction, and these macrophages promoted tissue repair by promoting the clearance of fibrotic and apoptotic cells." (PMID 36569953, 2022). "SPP1 specifically appeared after myocardial infarction and was almost exclusively produced by galectin-3+CD206+ macrophages." (PMID 36569953, 2022). "A significantly increased galectin-3 expression has been demonstrated in the early phase of acute myocardial infarction (AMI) and ACS." (PMID 35053194, 2021). "The role of Galectin 3 in the process of cardiac remodeling has been shown in experimental models of cardiomyopathy hypertrophy and myocardial infarction." (PMID 32318058, 2020). "Inhibition of the mitochondrial NADPH oxidase 4 (mitoNox)/PKC-α/galectin-3 (Gal-3) pathway can decrease left ventricular fibrosis following myocardial infarction." (PMID 32038243, 2019). "In an acute myocardial infarction, myocytes necrosis and an increased stretching of the infarcted ventricular wall segment, stimulate the production of galectin-3 by macrophages in the process of affected ventricular wall reparation." (PMID 29118378, 2017). "Previous publications have suggested that galectin-3 can be viewed as a useful predictor for new-onset AF during hospitalization due to acute myocardial infarction, as well as to later occurrence of AF, during follow-up." (PMID 29118378, 2017). "Galectin-3 is present in most tissues in normal conditions and overexpressed in myocardium from the early stages of HF, especially post-myocardial infarction (MI)." (PMID 26116131, 2014). "The aim of this study is to test the ability of 123I-galectin-3 (IG3) to assess cardiac remodeling in a model of myocardial infarction (MI) using imaging techniques." (PMID 26116131, 2014). "The serum galectin-3 level was measured, classified into two groups according to the median galectin-3 level (9.52 ng/ml, interquartile range 7.31–12.81), and compared with the composite of all-cause mortality, non-fatal myocardial infarction (MI), and stroke." (PMID 40747494, 2025). "Therefore, we were unable to determine the dynamic of LGALS-3 mRNA expression over time, that is, to assess the trend from the early to late phase of myocardial infarction." (PMID 39767568, 2024). "Accumulated galectin-3 directly activates the dectin-1 receptor, thereby potentiating platelet aggregation, and ATP release in the blood, which contributes to the development of thrombosis and myocardial infarction." (PMID 36873388, 2023). "Therefore, TD139 was proposed as a potent galectin-3 inhibitor improving atherothrombosis and myocardial infarction." (PMID 36873388, 2023). "However, in order to more accurately estimate the strength of the association of the haplotypes investigated with the incidence of myocardial infarction, LGALS-3 mRNA levels and protein expression, replication, and validation in a larger sample size is needed." (PMID 36672849, 2022). "A group of researchers made an attempt to find a correlation between levels of serum galectin-3 and NT-proBNP and the inflammatory condition assessed by serum hsCRP concentration in patients with the first myocardial infarction, treated by percutaneous coronary intervention (PCI)." (PMID 35053194, 2021). "Galectin 3 was an independent predictor of all-cause mortality, while it was not able to predict the development of angina pectoris or myocardial infarction." (PMID 31035456, 2019). "We measured galectin-3 only once at baseline, on the third day after acute myocardial infarction." (PMID 29118378, 2017). "Galectin-3 has been reported to have beneficial effects on the outcome of wound healing, infarct size, macrophage infiltration, fibrosis, ventricular remodeling, ventricle dilation, and heart function, particularly when present in the early phase after myocardial infarction." (PMID 37840130, 2023).
myocardial infarction (continued). "Moreover, after myocardial infarction, galectin-3 may contribute to the healing response by reducing injured cells." (PMID 32294902, 2020). "Its downregulation has been shown to mitigate myocardial ischemia, reperfusion injury, and cardiac hypertrophy post-acute myocardial infarction by influencing the miR-2054/AKT3 and miR-204-5p/LGALS3 pathways." (PMID 41169895, 2025). "IL-10 has been reported to increase the expression of intracellular galectin-3 through the activation of STAT3 in macrophages, which is essential for osteopontin-producing reparative macrophage polarization after myocardial infarction." (PMID 34987647, 2022). "Trials included using galectin-3 to estimate prognosis in myocardial infarction (MI) patients." (PMID 32455000, 2020). "In a study with patients with acute myocardial infarction treated with PCI, an independent predictive value of galectin-3 has been demonstrated in reinfarction occurence, early after the first myocardial infarction." (PMID 29118378, 2017). "The aim of this study was to determine whether elevated galectin-3 and MR-proANPlevels are predictors of MACE in patients with acute myocardial infarction (AMI)." (PMID 39077714, 2022). "In a study that compared galectin-3 levels in patients with myocardial infarction and with or without AF the patients with AF had higher levels of C-reactive protein (p < 0.01) and galectin-3 (p < 0.05) than those without AF." (PMID 35859594, 2022). "As with LGALS3, PTX3 expression was found to be increased under diseased conditions, and pentraxin-3 has been defined as a novel and independent prognostic marker of mortality after acute myocardial infarction (AMI) and IS." (PMID 34946887, 2021). "High levels of intracellular galectin-3 expression are essential for the transcriptional activation of osteopontin [OPN; also known as secreted phosphoprotein 1 (Spp1)] in STAT3-mediated macrophage M2 polarization after myocardial infarction." (PMID 34307396, 2021). "It was found that in individuals aged <40 years after myocardial infarction, serum galectin-3 concentration was strongly positively related to non-HDL-cholesterol concentration and negatively related to HDL-cholesterol level." (PMID 35053194, 2021). "Data on the usefulness of the integrated use of Galectin 3 and Galectin 3 binding protein in the setting of acute myocardial infarction are lacking." (PMID 31035456, 2019). "It is not known whether galectin-3 levels fluctuate in plasma early after acute myocardial infarction, or during the 15-months period that served as a follow-up in our study." (PMID 29118378, 2017).
liver fibrosis (93 papers, 2012 to 2026). "Differential gene expression analysis within the macrophage identified LGALS3 (encoding Galectin‐3) as one of the most prominently upregulated genes in liver fibrosis." (PMID 41168966, 2026). "In hepatic disease, particularly in metabolic dysfunction associated fatty liver disease, Galectin-3 has emerged as a promising biomarker for liver fibrosis." (PMID 41235339, 2025). "Circulating biomarkers that are associated with liver fibrosis hyaluronic acid was significantly elevated in the obese group, while galectin-3 and tissue inhibitor of metalloproteinase (TIMP)-1 were comparable in both groups." (PMID 40806703, 2025). "In cirrhosis, Galectin-3 is closely associated with the activation of hepatic stellate cells, a key step in liver fibrosis." (PMID 40417691, 2025). "Mice deficient in galectin-3 were protected from carbon tetrachloride-induced liver fibrosis and non-alcoholic steatohepatitis (NASH)." (PMID 38731984, 2024). "It is closely associated with CCM because galectin-3 levels are significantly increased in cirrhotic patients and animal models of liver fibrosis." (PMID 38892040, 2024). "Galectin-3 is a pro-fibrotic β-galactoside binding lectin highly expressed in fibrotic liver and implicated in hepatic fibrosis." (PMID 39144627, 2024). "Galectin-3 expression in peripheral blood and liver is associated with the progression of chronic and acute liver failure, liver fibrosis, HCC, and other liver diseases." (PMID 37180150, 2023). "Galectin-3 (Gal-3), which is a β-galactoside binding protein, has been associated with liver fibrosis, but its role in NAFLD remains elusive." (PMID 31337151, 2019). "We identified a PPI network module associated with liver fibrosis that includes known liver fibrosis-relevant genes like Timp1, Lgals3, Ctgf, and Lcn2, along with several new genes." (PMID 25380136, 2014). "We identified a PPI network module associated with liver fibrosis that includes known liver fibrosis-relevant genes, such as tissue inhibitor of metalloproteinase-1, galectin-3, connective tissue growth factor, and lipocalin-2." (PMID 25380136, 2014). "However, galectin-3 loss or inhibition is protective in most animal models of liver fibrosis but exacerbates the severity of autoimmune liver disease." (PMID 40649879, 2025). "In particular, galectin-3 has been associated with liver fibrosis." (PMID 39144627, 2024). "Galectin-3 protein (gal-3), a member of a family of proteins which have the property of binding to terminal galactose residues in glycoproteins, has been implicated in the pathogenesis of liver fibrosis as well as in other organ fibrogenesis." (PMID 24367597, 2013). "GR-MD-02 (belapectin), an inhibitor of galectin-3 that reduces liver fibrosis, was evaluated for its safety and efficacy in patients with MASH, liver cirrhosis, and PH." (PMID 39997697, 2025). "Literature data regarding the effect of LGALS3 ablation on hepatic steatosis, inflammation and liver fibrosis are still contradictory." (PMID 40608687, 2025). "Interest in galectin-3, which plays a role in liver fibrosis, has increased exponentially in recent years." (PMID 40292099, 2025). "Biomarkers such as Thrombospondin-1 (TSP-1), Galectin-3 (Gal-3), and Cystatin C (Cys-C) have been studied for their roles in assessing liver fibrosis and predicting cirrhosis progression." (PMID 40417691, 2025). "Of particular interest is galectin-3 (Gal-3), which is highly expressed by macrophages in disease states relevant to hepatic fibrosis." (PMID 41586160, 2025). "Currently, the effects of galectin-3 inhibitors are being investigated in patients with liver fibrosis." (PMID 38731984, 2024). "In liver fibrosis, galectin-3 is required for TGF-β-mediated fibroblast activation and ECM production." (PMID 39194690, 2024).
liver fibrosis (continued). "Several macrophage-targeted attempts to improve or prevent liver fibrosis have recently been reported, including dexamethasone-induced polarization into antifibrotic macrophages in murine models and galectin-3 inhibitors under clinical investigation." (PMID 38318455, 2024). "Galectin-3 mediates Schistosoma-induced liver fibrosis via the regulation of host immune cells, especially macrophages." (PMID 37817269, 2023). "Galectin-3−/− mice had milder liver fibrosis after CCl4 administration compared with wild-type animals." (PMID 37513890, 2023). "Galectin-3 levels are significantly increased in cirrhotic patients and animal models of liver fibrosis." (PMID 37513890, 2023). "An anti-inflammatory drug from the lectin family that has an important function in the treatment of liver fibrosis is called the galectin-3 antagonist." (PMID 36985782, 2023). "All the data above demonstrated that Galectin-3 plays a central role in the activation of hepatic stellate cells and liver fibrosis." (PMID 37513890, 2023). "A recent study indicated that the galectin-3 inhibitor belapectin reduced hepatic fibrosis in patients with MASH." (PMID 37960230, 2023). "It is secreted mainly by macrophages in disease states, and galectin-3-deficient mice are protected from NASH progression and liver fibrosis." (PMID 35453652, 2022). "Second, galectin-3 modulates the phagocytosis-induced hepatic stellate cell activation and liver fibrosis in vivo." (PMID 34778306, 2021). "Belapectin, an inhibitor or galectin-3 has shown potent anti-fibrotic efficacy in mouse and rat models of liver fibrosis and was well tolerated in a phase 1 clinical trial." (PMID 32260126, 2020). "Galectin-3 is produced by activated macrophages and contributes to liver fibrosis, and recombinant AnxA1 prevented galectin-3 expression." (PMID 31337068, 2019). "Galectin-3 antagonist Galectin-3 protein expression, which is essential to the development of hepatic fibrosis, was increased in NASH with the highest expression in macrophages surrounding lipid-laden hepatocytes." (PMID 29247356, 2018). "Another target molecule is Galectin-3 (Gal-3), pleiotropic β-galactoside-binding lectin, that was shown to play an important role in the liver fibrosis." (PMID 27999454, 2016). "GR-MD-02 (galactoarabino-rhamnogalacturonate) is a potent inhibitor of Galectin-3 that showed remarkable therapeutic effects in thioacetamide-induced liver fibrosis in rats and was submitted for 3 clinical studies concerning liver fibrosis." (PMID 27999454, 2016). "Galectin-3 protein is critical to the development of liver fibrosis because galectin-3 null mice have attenuated fibrosis after liver injury." (PMID 24130706, 2013). "For example, galectin-3 null mice are resistant to developing liver fibrosis due to carbon tetrachloride, and to the development of steatohepatitis and fibrosis when fed a high fat diet." (PMID 24130706, 2013). "In this study we have evaluated the effect of complex carbohydrate drugs that bind to galectin-3 protein, as well as galectin-1, using a model of hepatic fibrosis and cirrhosis in rats." (PMID 24130706, 2013). "Taken together, the results obtained in our experimental model confirm the previous studies suggesting that LGALS3 ablation may prevent hepatic steatosis and attenuates liver fibrosis." (PMID 40608687, 2025). "Furthermore, experimental models of liver fibrosis have demonstrated the protective effects of galectin-3." (PMID 40649879, 2025). "Moreover, the clinical utility of galectin-3 assessments is being explored in other chronic inflammatory conditions, such as chronic kidney disease, rheumatoid arthritis, systemic sclerosis and liver fibrosis." (PMID 41226478, 2025). "Galectin-3 is a β-galactoside-binding lectin involved in multiple cellular activities, including cell proliferation, apoptosis, inflammation, and migration in various tumors, heart disease, autoimmune disease, and liver fibrosis." (PMID 38340242, 2024).